IL13 (interleukin 13)
Diseases named in the same sentence as IL13 in open-access papers (continued):
Sharing a sentence is not in itself a finding about the gene and the disease.
asthma (continued). "IL-4 and IL-13 orchestrate asthma-associated inflammation and are Th2 cytokines that are produced not only by lymphocytes but also by mast cells, eosinophils and macrophages." (PMID 24040386, 2013). "In conclusion, results from this meta-analysis suggested that IL-13 +1923C/T polymorphism was a risk factor of asthma." (PMID 23841068, 2013). "This variant has been repeatedly associated with asthma as well as being shown to result in a distinct isoform of IL-13 with increased biological activity." (PMID 23886662, 2013). "Numerous other genes have been associated with asthma and related phenotypes, including those related to T helper cell (Th) pathways (IL-4, IL-13, IL-4Rα, TNFα and LTΑ)." (PMID 23573270, 2013). "It was observed from the data that asthma patients carrying the −1111CC homozygous wild-type alleles (P < 0.001) and −1111TT homozygous mutant alleles produced significantly higher IL-13 compared to control subjects carrying the same genotypes." (PMID 23865080, 2013). "In present study, we explored the associations between IL-13 genotypes/haplotypes, household carpet use and asthma phenotypes among children." (PMID 23382814, 2013). "There are controversies on the association between interleukin-13 (IL-13) +1923C/T polymorphism (rs1295686) and the risk of asthma." (PMID 23841068, 2013). "Our results show that the −1111T mutant allele are associated with asthma and the 4257A mutant alleles are associated with elevated IL-13 production." (PMID 23865080, 2013). "The results indicated that IL13 -1112C/T polymorphism was significantly associated with asthma risk (OR = 1.20, 95% CI 1.08–1.34, P = 0.0009) in a dominant genetic model." (PMID 23437086, 2013). "Our population did provide evidence for IL-13 genetic variants on asthma phenotypes among Han children." (PMID 23382814, 2013). "IL-13 +1923C/T polymorphism was still found to be associated with an elevated asthma risk in high quality studies." (PMID 23841068, 2013). "Genetic variants in the IL13 gene region have shown association with asthma, eczema, allergic rhinitis, and increased IgE levels in multiple studies of diverse race/ethnic backgrounds." (PMID 23815671, 2013). "To further investigate the interactions of household factors and IL-13 variants on children's respiratory health, we examined the relationships of household carpet use with asthma phenotypes." (PMID 23382814, 2013). "In conclusions, IL-13 genetic variants showed significant adverse effects on asthma phenotypes among children." (PMID 23382814, 2013). "We have previously shown that IL13 polymorphism modifies the impact of in utero tobacco smoke exposure on childhood asthma, suggesting a role for gene-environment interaction." (PMID 24314122, 2013). "In the present meta-analysis, we explored the association between the IL-13 −1112C/T and +2044A/G polymorphisms and asthma risk, including 34 eligible case-control studies." (PMID 23437086, 2013). "There was a significant association between IL-13 +1923C/T polymorphism and asthma risk in codominant model." (PMID 23841068, 2013). "In the subgroup analysis by ethnicity, there were significant associations between IL13+2044A/G polymorphism and asthma risk in Asians (OR = 1.19, 95% CI 1.04–1.36, P = 0.01) and Caucasians (OR = 1.22, 95% CI 1.06–1.40, P = 0.005) but not in African Americans." (PMID 23437086, 2013). "Results from our study suggested that the IL-13 +1923C/T polymorphism was significantly associated with the risk of asthma." (PMID 23841068, 2013). "After careful review, ten eligible case-control studies on the relationship between IL-13 +1923C/T polymorphism and asthma risk were included in this meta-analysis." (PMID 23841068, 2013). "IL-13 and mucus production are not only associated with IL-17 production but a feature of virally-exacerbated asthma." (PMID 23462708, 2013).
asthma (continued). "When stratified by ethnicity, IL-13 +1923C/T polymorphism remained significantly associated with higher asthma risk in Asians and Caucasians." (PMID 23841068, 2013). "Thirty-one case-control studies identified an association between IL-13+2044A/G polymorphism and asthma risk." (PMID 23437086, 2013). "This suggests that different polymorphisms identified are capable of altering the function of IL-13 and thus contributing to a predisposition to asthma." (PMID 23865080, 2013). "While requiring replication in an independent cohort, the results show the interplay of prenatal maternal smoking, genetic variants and DNA-M of IL13 influencing asthma-related lung function." (PMID 24314122, 2013). "Multiple logistic regression models with false-discovery rate (FDR) adjustments were fitted to estimate the effects of IL-13 variants on asthma phenotypes." (PMID 23382814, 2013). "Two functional SNPs, rs20541 and rs1800925, of the IL-13 gene (IL13) have been frequently associated with asthma-related lung functions." (PMID 24314122, 2013). "IL-13 has been implicated in a variety of allergic responses, including airway hypersensitivity, mucus hypersecretion, AR, and asthma." (PMID 23965966, 2013). "A number of studies have investigated the association between IL-13 +1923C/T polymorphism and asthma risk, but the results were controversial and underpowered." (PMID 23841068, 2013). "This study identified that treatment with IL13 caused dysregulation of a number of asthma-related genes." (PMID 22500180, 2012). "A recent study showed that the excessive production of interleukin (IL)-4, IL-5, and IL-13 by T-helper type 2 (Th2) cells is implicated in the development of asthma." (PMID 22203879, 2012). "Interleukin-13 (IL-13) is an immunoregulatory cytokine that has been reported to have some polymorphisms in it gene associated with same disease especially asthma and allergy." (PMID 23108822, 2012). "The human variant of the 15-LOX enzyme in monocytes and alveolar macrophages can be induced by interleukins associated with asthma, including IL-4 and IL-13." (PMID 21897859, 2011). "The IL-4, IL-13, and IL-4Rα interaction pathway have been implicated in the pathogenesis of AR and asthma." (PMID 22087298, 2011). "More than 10 papers report an association between single nucleotide polymorphisms (SNP) in IL-13 and the effects on asthma in adults and in children, in the context of infections, atopy, IgE levels, or risk for asthma." (PMID 23283176, 2011). "Studies utilizing haplotype and multigene analysis have made similar associations of IL-13 SNPs and asthma." (PMID 23283176, 2011). "In previous studies, the C-1055T and Arg130Gln polymorphisms in the IL13 gene have been associated with total serum IgE levels, atopy, asthma and AR." (PMID 22087298, 2011). "The chromosome 5q31 locus which has been linked to blood P. falciparum parasites density also contains the genes encoding the cytokines IL-4, IL-5, and IL-13, and these have been associated with inflammatory diseases including asthma." (PMID 22216286, 2011). "Birth order and IL13 polymorphisms have each been previously found to be separately associated with allergy, asthma and atopic markers in childhood." (PMID 20403202, 2010). "In particular, polymorphisms of IL-4RA and IL-13 have been associated with elevated IgE levels and asthma severity." (PMID 20298583, 2010). "If the resultant inflammatory response is T helper-2 dominant, cytokine mediators typically associated with asthma [interleukin (IL)-4, IL-5, IL-9, IL-13] would subsequently be produced." (PMID 20064771, 2010). "The most prevalent gene symbol in the retrieved abstracts for genetic association with asthma was IL4 (91 citations) followed by IL13 (75 citations) and TNF (73 citations)." (PMID 21103062, 2010).
asthma (continued). "We are currently conducting studies in a mouse model of asthma exacerbation to investigate the efficacy of anti-IL-13 mAb therapy on the decline in lung function and AHR caused by exposure to HDM with concomitant viral infection." (PMID 20957211, 2010). "For example, IL13 has been associated with asthma at least 11 times as well as to the asthma sub-phenotype immediate hypersensitivity 4 times." (PMID 20092628, 2010). "In asthma we found a positive association of IL-4 with IL-5, and significant association with IL-13, TNF α as well as GM-CSF, while IL-5 is positively associated with IL-4, IL-10 and GM-CSF." (PMID 20616938, 2010). "After subgroup analysis by age, the ACE D/I, β2-Adrenergic Receptor (β2-AR) -79G/C, TNF-α -308G/A, Interleukin 4 receptor(IL-4R) -1902G/A and IL-13 -1923C/T polymorphisms were found significantly associated with asthma risk in Chinese children." (PMID 20868478, 2010). "IL-4RA and IL-13 polymorphisms in children with Alternaria-sensitive moderate-severe asthma compared to Alternaria-sensitive mild asthma." (PMID 20298583, 2010). "Development of airway hyperreactivity and hyperresponsiveness to innocuous stimuli is a diagnostic and pathological feature of asthma that can be recapitulated in animal models of allergic airway inflammation, and has been linked to increased airway IL-13." (PMID 20573261, 2010). "Polymorphisms of the IL-4 receptor alpha chain (IL-4RA) and IL-13 have been associated with elevated IgE levels and asthma severity." (PMID 20298583, 2010). "Up to date, we first found that ADAM33 T1-C/T, ACE D/I, IL-13 -1923C/T, RANTES -28C/G and IL-13 -2044A/G polymorphisms were associated with risk of asthma in Chinese population by using meta-analyzes." (PMID 20868478, 2010). "Elevated chitinase has been associated with asthma and elevated IgE levels perhaps through an IL-13 pathway." (PMID 20298583, 2010). "Arginase-1 in macrophages is induced by Th2 type cytokines such as IL-4, IL-10, IL-13 and IL-21 and increased arginase is associated with resistance to worm infections, allergic conditions such as asthma and Th2 induced pathologies." (PMID 19696894, 2009). "In summary, PT, CR and their combinational prescription have deep inhibitory effects on airway inflammation in a murine model of asthma and it was caused by suppression of Th2 cytokines (IL-4, IL-5, IL-13), IgE, eosinophil CCR3 expression in lung." (PMID 19657453, 2009). "Interleukin-13 (IL-13) is a Th2 cytokine with anti-inflammatory properties which has been implicated in the pathogenesis of asthma." (PMID 18949100, 2008). "Previous studies from our laboratory showed that CD38 expression and its enzymatic activities are augmented by TNF-α and IL-13, cytokines that are implicated in the pathogenesis of inflammatory airway diseases such as asthma." (PMID 18341691, 2008). "IL-13 is a Th2 cytokine that has been implicated in allergy and asthma airway inflammation, airway remodelling and bronchial hyperresponsiveness." (PMID 18460189, 2008). "Interleukin-13 (IL13) is a good candidate as an asthma susceptibility gene because it is a cytokine produced by Th2 cells and because its genetic location on chromosome 5q31 has been linked to asthma and related phenotypes in multiple linkage studies." (PMID 18197984, 2008). "The functional polymorphism, IL-13 Arg130Gln, was associated with raised IgE in asthma patients and this was selected in our study." (PMID 18949100, 2008). "In summary, in a sub-sample of the Isle of Wight cohort, the combined effect of exposure to tobacco smoke during pregnancy and the common haplotype pair of the IL13 gene resulted in an increased relative risk of early-onset persistent wheeze and asthma." (PMID 18186920, 2008). "In particular, in the development of increased asthma severity, investigators have reported that another combination of the ile75val IL-4Rα SNP and arg110gln IL-13 SNP has also been associated with allergy and asthma." (PMID 16503977, 2006).
asthma (continued). "Some reports demonstrate that IL-13 is overproduced in asthma and have implicated IL13 in pathogenesis of inflammation and airway remodeling responses." (PMID 16083514, 2005). "A haplotype comprised of the IL13_+1923T and IL13_130Gln alleles was also strongly associated with asthma in this sample." (PMID 16336695, 2005). "Th2 cytokines IL-4 and IL-13 cause AECs dysfunction in asthma." (PMID 41555513, 2026). "Therefore, monitoring IL-13 levels can assist clinicians in timely identifying children at high risk for poor asthma control and taking corresponding intervention measures." (PMID 40260311, 2025). "Furthermore, levels of OVA‐specific IgE and Th2‐associated cytokines (IL‐4, IL‐5, IL‐13) in BALF were significantly reduced in the sLNP‐OVA/Cel treated group compared to other asthma treatment groups." (PMID 39921498, 2025). "This modulation may lead to a decreased demand for AMCase activity, as IL-13 is a critical driver of AMCase expression and is associated with the Th2-mediated inflammatory response observed in asthma." (PMID 39806495, 2025). "Woodruff et al31 demonstrated that TH2-high and TH2-low asthma phenotypes, currently often referred to as type 2–high and type 2–low asthma phenotypes, can be differentiated on the basis of the expression levels of IL-13– and IL-13–inducible genes, including POSTN, which encodes periostin." (PMID 40687950, 2025). "These lower IL‐13 levels may also be associated with lower TSLP levels in males with asthma compared with females." (PMID 40022441, 2025). "Furthermore, while all DGDG variants induced the production of the Th1 cytokine IFN-γ, only DGDG-2 and DGDG-3 triggered the release of the Th2 cytokine IL-13, a cytokine implicated in allergic inflammatory responses such as asthma." (PMID 40599773, 2025). "We did not directly compare HDM exposure between our mixed background mice and C57BL/6 mice, which are generally more prone to neutrophilic inflammation in ovalbumin-induced asthma models, which may underlie the weaker IL-4, IL-5 and IL-13 responses observed." (PMID 41146597, 2025). "Released following airway epithelial injury, it activates the ST2 receptor, induces the production of IL-4, IL-5, and IL-13 by Th2 cells, mast cells, and other cell types, drives eosinophilic inflammation and airway hyperresponsiveness, and is closely linked to asthma susceptibility." (PMID 41561024, 2025). "However, persistent overexpression of IL-13 has been associated with chronic inflammation and tissue remodeling in diseases such as asthma and fibrosis." (PMID 40796247, 2025). "The increased understanding of such complex inflammatory pathways has resulted in the development of antibody-based biological therapies that target T2 cytokines such as IL-4, IL-5, and IL-13, which play key roles in the inflammatory processes underlying asthma." (PMID 41440490, 2025). "Furthermore, different studies have shown that Mg2+ can interfere with the activation of NF-κB, a central pathway in the transcription of proinflammatory genes, such as TNF-α, IL-4, IL-5, and IL-13, all of which are implicated in asthma pathophysiology." (PMID 40868515, 2025). "It is possible that in these individual animals the response was tending towards an asthma-like scenario as we know that IL-13 is a key cytokine causing antibody isotype switching to the production of IgE and it is well known that it is a typical scenario for BRSV pathogenesis." (PMID 40261882, 2025). "Moreover, interleukin (IL)-4, IL-5, and IL-13 represent key cytokines implicated in the progression of asthma." (PMID 40723867, 2025). "Our central aim was to elucidate mechanisms by which IL-13 affects epithelial responses to rhinovirus infection to provide novel insights into why rhinovirus infection is associated with severe exacerbation in children with uncontrolled T2-asthma." (PMID 41427379, 2025).
asthma (continued). "T2 asthma is associated with an increased susceptibility to allergens, which triggers immune responses involving eosinophil recruitment and the production of cytokines such as IL-4, IL-5 and IL-13." (PMID 40070355, 2025). "Dupilumab, a fully human anti-IL-4 receptor-α monoclonal antibody, blocks IL-4 and IL-13 signaling to downregulate itching-associated cytokines, chemokines, and IgE levels, which has been applied in allergic diseases treatment, i.e., AD and asthma treatment." (PMID 39975679, 2025). "In addition, stress has a stimulating effect on the production of certain cytokines (e.g., interleukin (IL)‐4, IL‐5, IL‐13) associated with asthma." (PMID 40702946, 2025). "Currently, there is extensive research on asthma susceptibility genes, confirming associations with genes such as interleukin-4 (IL-4), interleukin-13 (IL-13), β2 adrenergic receptor (ADRB2), Zona Pellucida Binding Protein 2 (ZPBP2), and numerous other candidate genes." (PMID 40433469, 2025). "In asthma, anti-IL-13 therapies have been associated with improved lung function, particularly in patients with peripheral eosinophil counts ≥ 300 cells/μL and elevated sputum IL-13 levels." (PMID 41002723, 2025). "Type 2 (T2)-high asthma, characterized by eosinophilic inflammation and elevated IL-4, IL-5, and IL-13 pathways, has been associated with a more robust Th2 response, which may mitigate the hyperinflammatory state triggered by SARS-CoV-2 infection." (PMID 41149067, 2025). "Our understanding of the complex patterns of inflammation underlying asthma pathogenesis has informed the development of antibody-based biological therapies that target the T2 cytokines, IL-4, IL-5, and IL-13, in adults and in adolescents and children with refractory asthma." (PMID 41440490, 2025). "Sputum IL-13 may be a helpful biomarker in assessing asthma control, as higher sputum IL-13 levels have been linked to poor asthma control." (PMID 40863432, 2025). "A decreased ratio of IFN‐γ to IL−13 (IFN‐γ:IL‐13) secretion by mitogen‐stimulated maternal peripheral blood mononuclear cells isolated during the third trimester of pregnancy was associated with increased prevalence of childhood asthma." (PMID 39625247, 2025). "IL-4, IL-5, IL-10, and IL-13 are key cytokines involved in the immune response, playing a significant role in the recruitment and activation of eosinophils, a hallmark of the allergic inflammatory response seen in asthma." (PMID 40951891, 2025). "Consequently, changes in the mRNA expression levels of the five major IL-4/IL-13 pathway genes, which are DNA variants, lead to gene expression changes, which lead to asthma susceptibility and subsequently elevated serum IgE." (PMID 40375219, 2025). "Chronic inflammation is driven by type-2 cytokines, particularly interleukin (IL) -4, IL-5, and IL-13, thus it is often associated with other comorbidities that share the same underlying pathological mechanisms, such as asthma, allergic rhinitis (AR), and atopic dermatitis (AD)." (PMID 39404884, 2025). "Gene variants encoding immune regulators, such as IL-4 and IL-13, had been linked to an increased chance of developing asthma; these cytokines orchestrate pathways of IgE class switching and Th2 differentiation, driving key pro-inflammatory features within the airway." (PMID 40337626, 2025). "The mechanism by which dupilumab improves asthma control and reduces exacerbation while eosinophils are persistent may be linked to an impact of IL-4 and IL-13 on mucus secretion and airway smooth muscle." (PMID 38291489, 2024). "In addition, asthma conditions have been linked to increased levels of inflammatory cytokines such as IL-4, IL-5, IL-17, IL-13, and TNF-α in addition to decreased IFN-γ and IL-10." (PMID 39295946, 2024). "However, in contrast to our findings, studies from Malaysia and China reported a highly significant association of the SNP-1111C>T of IL-13 with asthma." (PMID 38699097, 2024).